HMGB1 (high mobility group box 1)
Diseases named in the same sentence as HMGB1 in open-access papers (continued):
Sharing a sentence is not in itself a finding about the gene and the disease.
tumor (continued). "Although high mobility group box 1 (HMGB1) reportedly plays a vital role in tumor radioresistance by modulating DNA damage repair, the precise mechanisms remain unclear." (PMID 41875183, 2026). "In the myeloid compartment, TIM-3 restricts the activation of the cGAS-STING pathway in tumor-infiltrating DCs by limiting the uptake of extracellular DNA and by sequestering high-mobility group box 1 (HMGB1), an alarmin that facilitates nucleic acid-mediated innate immune sensing." (PMID 41486149, 2026). "The dying cancer cells release damage-associated molecular patterns (DAMPs), such as high mobility group box 1 (HMGB1) and calreticulin (CRT), into the tumor microenvironment, promoting dendritic cell maturation and recruiting immune cells for the amplification of ICD." (PMID 40797208, 2025). "Furthermore, compared to single treatments, the combination of carboplatin and KHSRP knockdown further reduced KHSRP, HMGB1, N-cadherin, vimentin, and Ki67 levels, and increased E-cadherin levels in mouse tumor tissues." (PMID 41194272, 2025). "In this context, the increase in HMGB1 observed in the RO group may represent an immunomodulatory mechanism that favors immune activation and tumor surveillance, contrasting with the suppressive effect seen with high-dose conventional chemotherapy." (PMID 40943044, 2025). "HMGB1 is released following the death of tumor cells, which stimulates an inflammatory response and facilitates antigen presentation, thereby enhancing the tumor recognition capability of the immune system." (PMID 41383334, 2025). "Moreover, lactylation reduces the binding affinity of HMGB1 for immune cell surface receptors, impairing immune cell recognition and clearance of HMGB1, suppressing anti-tumor immune responses, and promoting cancer progression." (PMID 40584966, 2025). "In addition, within the tumor microenvironment, hypoxia further amplifies the necroptosis-HMGB1 axis to drive resistance and metastasis." (PMID 41465435, 2025). "Among these, HMGB1 has been shown to play a key role in tumor progression." (PMID 41332426, 2025). "HMGB1 enhances anti‐tumor immunity by promoting dendritic cell (DC) maturation and activation via immune stimulation, thereby improving their capacity to efficiently present tumor antigens to T cells." (PMID 41354099, 2025). "Hence, HMGB1-necroptosis axis critically impact the therapeutic outcomes, where the initial inflammatory signal triggered by HMGB1 release can be subverted to support tumor survival, immune evasion, and treatment resistance across several cancer types." (PMID 41465435, 2025). "Last of all, we also performed the subcutaneous tumour model and found that targeting HMGB1 could suppress the in vivo growth of tumours derived from the PHF10‐deleted cells, as evidenced by the quantification of tumour growth curve and tumour weight." (PMID 39904827, 2025). "Affects tumor progression, angiogenesis, and metastasis via NF‐κB/HMGB1 axis." (PMID 41409896, 2025). "Serum levels of pyroptosis markers (NLRP3, HMGB1, and caspase‐1) and conventional tumor markers, including carcinoembryonic antigen (CEA), cancer antigen 125 (CA125), and cancer antigen 15‐3 (CA15‐3), were measured using enzyme‐linked immunosorbent assay (ELISA) kits." (PMID 41479846, 2025). "Since NF-κB activation is closely associated with tumor invasion and metastasis, primarily through the regulation of matrix metalloproteinase-2 (MMP-2), we subsequently examined the MMP-2 signal in MDA-MB-468 cells treated with HMGB1." (PMID 40277915, 2025). "Finally, the release of high-mobility group box 1 (HMGB1) protein promotes DC maturation and the presentation of tumor antigens to T-cells." (PMID 41154386, 2025). "However, in specific therapeutic contexts, autophagic HMGB1 release can stimulate anti-tumor immunity and enhance treatment efficacy." (PMID 41465435, 2025). "Additionally, the release of HMGB1 by NETs activates TLR9 signaling in tumor cells, enhancing their metastatic potential." (PMID 40995363, 2025).
tumor (continued). "We hypothesized that HMGB1 alterations may correlate with more aggressive clinicopathological features in different tumor types." (PMID 40804938, 2025). "Conversely, HMGB1 can enhance anti‐tumor immunity by activating dendritic cells and T cells." (PMID 41354099, 2025). "Furthermore, organoids derived from patients have illustrated that the modulation of the macrophage-capping protein (MCP)-GPX4/HMGB1 pathway can instigate immunogenic ferroptosis, thereby presenting a novel strategy to bolster anti-tumor immune responses." (PMID 40427552, 2025). "Moreover, the binding of HMGB1 to TLR-9 receptor induce tumor growth under hypoxic conditions, which was emphasized by our demonstration that the downregulation of HMGB1 reduced HCC cell growth." (PMID 40331953, 2025). "Radiotherapy can trigger the abscopal effect through immunogenic cell death, releasing tumor antigens and danger signals such as HMGB1 and calreticulin, which activate dendritic cells and prime cytotoxic CD8+ T cells via the cGAS–STING/type I interferon pathway." (PMID 41300968, 2025). "Especially, immunofluorescence analysis demonstrated that HAQ/223Ra@HNPs treatment markedly increased the expression of ER stress-related proteins (CHOP, GRP78, and PERK) and ICD markers (CALR and HMGB1), accompanied by a significant upregulation of PD-L1 in tumor tissues." (PMID 41320759, 2025). "In addition, it has been shown that high serum levels of HMGB1 or its expression at tumor sites correlate with poor prognosis and therapy outcomes." (PMID 40277915, 2025). "Notably, glycyrrhizin attenuated the tumor growth-promoting effect of lactate-stimulated SCs through HMGB1 inhibition." (PMID 40148311, 2025). "However, under chronic high‐dose HMGB1 exposure or specific TLR4 polymorphisms, the HMGB1‐TLR4 signal instead inhibits phagosome‐lysosome fusion, reduces tumor antigen cross‐presentation, and causes failed CD8+ T cell priming." (PMID 41354099, 2025). "This is manifested by insufficient infiltration of antigen-presenting cells (APCs), which results in the failure to effectively capture DAMPs (e.g., ATP, HMGB1) released by dying tumor cells, thereby inhibiting cross-presentation of antigens and activation of cytotoxic T lymphocytes (CTLs)." (PMID 40535125, 2025). "Furthermore, ferroptosis inducers can trigger ICD in tumor cells, leading to the release of high-mobility group box 1 (HMGB1) and ATP into the tumor microenvironment, as well as the plasma membrane translocation of calreticulin (CRT)." (PMID 40636119, 2025). "On the other hand, HMGB1 may attenuate radiotherapy sensitivity by promoting DNA damage repair and facilitating tumor cell recovery." (PMID 40969278, 2025). "Activation of the tumor-specific immune response is accompanied by the cell surface exposure of calreticulin and heat-shock proteins, the secretion of adenosine triphosphate, and the release of high mobility group box-1." (PMID 40207233, 2025). "First, experimental data indicate that various miRNAs (miR-129-5p, miR-505, and miRNA-1284, etc.), ginsenosides, and KLF4 can effectively suppress HMGB1 expression under in vitro conditions, significantly inhibit tumor cell proliferation and migration, and induce apoptosis." (PMID 41296391, 2025). "Additionally, SMI402, which effectively inhibits TIM-3 from binding to CEACAM-1, HMGB-1, and PtdSer, has demonstrated its capacity to suppress tumor growth by promoting the infiltration and activation of CD8+ T cells and NK cell at the tumor site." (PMID 40332725, 2025). "Another important consideration is the role of HMGB1 in modulating the tumor microenvironment." (PMID 40559922, 2025). "Notably, the HMGB1-mediated signaling network is involved in regulating tumor cell-intrinsic properties." (PMID 41296391, 2025). "HMGB1 exhibits a complex dual role in tumor progression and anti‐cancer therapy." (PMID 41354099, 2025).
tumor (continued). "Compared to the control group, the 15 mg/kg P1 treatment significantly increased the HMGB1 levels in the right tumors (injected tumor), with obvious diffuse positive signals in the extracellular matrix, indicating that P1 significantly increased the release of HMGB1 from tumor cells in vivo." (PMID 40733687, 2025). "Extracellular HMGB1 arouses inflammation, drives cell differentiation, and promotes tumor growth." (PMID 41163685, 2025). "This bidirectional regulation manifests in two ways: on one hand, ERS induces ICD through calreticulin exposure, HMGB1 release, and ATP secretion, enhancing anti-tumor immunity; on the other hand, it promotes immune suppression via mechanisms such as PD-L1 glycosylation." (PMID 41407677, 2025). "By contrast, fully oxidized HMGB1 loses affinity for RAGE and Beclin1 and instead enhances drug cytotoxicity by promoting apoptosis through the caspase-9/-3 intrinsic pathway, positioning HMGB1 as a molecular switch that regulates autophagy and apoptosis within the tumor microenvironment." (PMID 41465435, 2025). "Calcipotriol treatment significantly increased HMGB1 release by tumor cells in vivo." (PMID 39782693, 2025). "The tumor microenvironment amplifies this resistance loop, as shown in non-small cell lung cancer (NSCLC), where cancer-associated fibroblasts (CAFs) exhibit upregulated autophagy that is responsible for the secretion of HMGB1." (PMID 41465435, 2025). "However, HMGB1 released by tumor vesicles can also promote tumor invasion and metastasis through a series of post-transcriptional regulations." (PMID 40356601, 2025). "In addition, RAGE can be activated by HMGB1 released from necrotic tumor cells, which induces autophagy and inhibits apoptosis, thus enhancing cell resistance." (PMID 40969278, 2025). "Similarly, compared with those from untreated B16F10 cells, the secretion of HMGB1 and ATP from tumor cells was greatly increased, and the most significant increase was observed in the CPIP@EV–CM + US group." (PMID 40854883, 2025). "For example, irreversible electroporation (IRE) significantly alleviates the immunosuppressive microenvironment of pancreatic cancer by disrupting the integrity of tumor cell membranes, increasing the release of DAMPs such as HMGB1, and downregulating PD-L1 expression." (PMID 40535125, 2025). "However, HMGB1 expression in tumor cells promotes inflammation, angiogenesis, evasion of cell death, and survival of myeloid-derived suppressor cells (MDSCs) through the induction of autophagy and metastasis." (PMID 41375025, 2025). "Also, HMGB1 can activate or enhance anti-tumor immunity in a variety of ways during cancer development and treatment." (PMID 40969278, 2025). "However, the role of autophagy in HMGB1 release is also context-dependent and can, under specific conditions, lead to anti-tumor effects." (PMID 41465435, 2025). "Furthermore, tumor formation in 4T1 cells supports that the cytoplasmic HMGB1 expression is related to p-STAT3 and PD-L1 expression." (PMID 40389855, 2025). "Thus, in context-dependent manner, extracellular HMGB1 contributes to an adaptive microenvironment that can support tumor cell persistence under therapeutic stress." (PMID 41465435, 2025). "Further in vitro experiments using BMDMs and RAW264.7 cells demonstrated that the culture supernatant from HMGB1-deficient tumor cells treated with recombinant viruses failed to induce M1 polarization in BMDMs." (PMID 40082916, 2025). "Next, we sought to understand whether SCs stimulated with lactate promoted tumor progression through HMGB1." (PMID 40148311, 2025). "Subsequently, the effect of HMGB1 on tumor progression was confirmed by an in vitro study, which revealed that HMGB1 knockdown could suppress the proliferation, adhesion, migration, and invasion abilities of HuH-7 cells." (PMID 40331953, 2025).
tumor (continued). "In addition to assessing HMGB1 in tumor cells, we also explored the presence of serum HMGB1 at 24 and 72 hours post-ECT as a potential systemic biomarker of immunogenic cell death." (PMID 40007542, 2025). "Furthermore, we verified the functions of Vpr peptides in promoting CRT exposure, ATP, and HMGB1 release as the three hallmarks of Vpr peptide-induced tumor cell ICD." (PMID 40733687, 2025). "Upon infecting tumor cells, OV trigger immunogenic cell death (ICD), leading to the release of key damage-associated molecular patterns (DAMPs)—including high-mobility group box 1 (HMGB1), ATP, and calreticulin (CRT)." (PMID 40977706, 2025). "For example, certain circRNAs and lncRNAs not only regulate HMGB1 expression but may also indirectly influence the tumor microenvironment or immune response through unknown mechanisms." (PMID 41296391, 2025). "Based on the IPA of differentially expressed genes, we discovered activity changes of several pathways significantly associated with tumor behavior were activated over the course of surgery (FDR <5%), including IL-6, IL-8, HMGB1, HIF1α, IL-1, TGFβ, and TNFα signaling." (PMID 40331601, 2025). "Intracellular HMGB1 acts as a tumor suppressor by binding to tumor suppressor proteins such as Rb." (PMID 41296391, 2025). "During this process, changes in damage-associated molecular patterns (DAMPs) occur, including the high expression of calreticulin (CRT) on the dying tumor cell surfaces and the release of signaling molecules, such as high mobility group protein 1 (HMGB1) and adenosine triphosphate (ATP)." (PMID 40435257, 2025). "This suggests that HMGB1 may contribute to TNBC aggressiveness by promoting tumor progression and resistance to treatment." (PMID 40277915, 2025). "HMGB1 promotes tumor invasion and metastasis via activation of TLR4 and RAGE signaling pathways." (PMID 41354099, 2025). "When immune or tumor cells are stimulated by both internal and external factors, HMGB1 can be secreted into the extracellular space, where it binds to various receptors on the cell membrane, such as the advanced glycation end product (RAGE) receptor, Toll-like receptors, CXCL4, TIM-3, and others." (PMID 40975711, 2025). "Moreover, once the growth of a tumour exceeds its blood and nutrient supply, necrotic cell death in the tumour results in the release of various DAMPs, including IL-1 and HMGB1, both of which are related to lung inflammation." (PMID 39949769, 2025). "Given that heparanase and HMGB1 can both modulate the tumor microenvironment and facilitate metastasis, targeting these parallel pathways may offer synergistic benefits in aggressive cancers such as TNBC." (PMID 40277915, 2025). "It is widely believed that HMGB1 may directly contribute to tumor cell metastasis by modifying extracellular matrix components and regulating cell adhesion properties or enhance tumor cell progression by inducing MIA." (PMID 40148311, 2025). "Our study confirmed this finding; compared with ADVCtrl, the recombinant adenoviruses ADVNE and ADVPPE, which express NE and PPE, indeed induce pyroptosis in tumor cells, accompanied by the release of HMGB1—an essential factor driving the changes in the tumor microenvironment observed in this study." (PMID 40082916, 2025). "Furthermore, inflammatory mediators (e.g., IL-1β, HMGB1) and tumor antigens released during pyroptosis stimulate immunogenic cell death, promoting CD8+ T cell infiltration and dendritic cell maturation." (PMID 41311720, 2025). "The changes in the secretion of HMGB1 from tumor cells were evaluated using an ELISA." (PMID 40733687, 2025). "This process is driven by DAMPs released by tumor necrosis: for example, HMGB1 recruits neutrophils to the necrotic area by activating the TLR4/NF-κB pathway, forming a positive feedback loop of “necrosis-DAMP-TAN infiltration” that further amplifies the ferroptosis effect." (PMID 40535125, 2025).
tumor (continued). "And HMGB1 was distributed in a variety of cells, but tumor cells showed stronger expression." (PMID 40535567, 2025). "Interfering with HMGB1 or its signaling axis shows good antitumor potential in in vitro and in vivo models, but clinical transformation is still limited by its dual biological effects and tumor heterogeneity." (PMID 41296391, 2025). "Thus, TLR4 and HMGB1 play a critical role in the cross-presentation of tumor antigens from dying tumor cells by DCs to CD8+ T cells." (PMID 40362678, 2025). "Importantly, these reductions in tumor burden were accompanied by decreased HMGB1 expression in both tumor tissues and plasma, further supporting the role of HMGB1 as a driver of MM aggressiveness." (PMID 40559922, 2025). "These molecular alterations suggest that HMGB1 not only marks cellular stress and damage but may actively participate in autophagy-mediated tumor survival and progression." (PMID 41009692, 2025). "Similarly, HMGB1, a damage-associated molecular pattern (DAMP) molecule, recruits macrophages and dendritic cells to the tumor microenvironment, linking innate and adaptive immunity." (PMID 40396172, 2025). "Tumor cell-released HMGB1 serves as an immune regulator through classical RAGE-mediated signaling." (PMID 39893499, 2025). "Through this pathway, chemotherapeutic drug-induced tumor cell autophagy emits three signals: CRT exposure on the cell surface to stimulate DC phagocytosis, ATP release to recruit DCs and HMGB1 release to promote the stable binding of DCs to dying tumor cells and induce anti-tumor immune responses." (PMID 40051630, 2025). "Moreover, GEPIA data indicated that PRC1 had a positive expression correlation with ICD markers, including CD274 (PD-L1), CALR (CRT), and HMGB1 in tumor tissues from COAD and READ patients." (PMID 40847353, 2025). "Paradoxically, HMGB1 may also promote malignancy by enhancing tumor growth, metastasis, and immune evasion." (PMID 39789615, 2025). "In addition, in consistent with the results, the colony formation ability, migration ability, as well as self‐renewal ability were enhanced with PHF10 depletion, whereas HMGB1 knockdown impaired these tumour‐promoting properities." (PMID 39904827, 2025). "Additionally, in a mouse model overexpressing Lnc-PHF3-3, HMGB1-mediated autophagy activation and apoptosis inhibition were significantly enhanced, reducing tumor responsiveness to chemotherapy." (PMID 41296391, 2025). "Oncogenic and tumor suppressor properties of HMGB1 with examples." (PMID 40969278, 2025). "In addition, cell surface exposure of the endoplasmic reticulum calcium-binding protein calreticulin and extracellular release of HMGB1 occurred in chemotherapy-induced ICD of tumor cells." (PMID 40698137, 2025). "The HMGB1/RAGE axis has also promoted tumor cell proliferation in certain cancers." (PMID 40277915, 2025). "Simultaneously, CA‐4 and ES‐Cu jointly evoked the release of DAMPs signaling molecules such as CRT, HMGB1, and ATP, reversing the immunosuppressive tumor environment, which in turn triggered ICD and activated the T‐cell‐mediated immune response, thus further enhancing the anti‐tumor efficacy." (PMID 40323152, 2025). "HMGB1 exhibits both oncogenic and tumor‐suppressive effects in cancer." (PMID 41354099, 2025). "Lgals3 and Hmgb1 expression are also highly expressed in the tumour cell population." (PMID 40473819, 2025). "On one hand, HMGB1 can promote tumor growth, metastasis, and immune evasion." (PMID 41354099, 2025). "Interestingly, the same large amount of HMGB1 was released in dead cells after treatment with doxorubicin, which mediated the survival of chemoresistant tumor cells through TLR4/RAGE-sCLU." (PMID 40969278, 2025). "In the context of tumor therapy, HMGB1‐mediated autophagy promotes chemoresistance in cancer cells." (PMID 41354099, 2025).